FGFR3 (fibroblast growth factor receptor 3)
Diseases named in the same sentence as FGFR3 in open-access papers (continued):
Sharing a sentence is not in itself a finding about the gene and the disease.
glioma (44 papers, 2014 to 2025). A benign or malignant brain and spinal cord tumor that arises from glial cells (astrocytes, oligodendrocytes, ependymal cells). "Infigratinib (FGFR 1/2/3 inhibitor) showed limited efficacy in the entire recurrent glioma patients with the FGFR alterations population but demonstrated a durable response in patients with FGFR1 or FGFR3 point mutations and those with FGFR3-TACC3 fusions." (PMID 39272879, 2024). "Among gliomas with FGFR3::TACC3 fusion, age, TERT promoter mutation, pathological features, DNA-methylation profiling and fusion subtype are of interest to determine patients’ risk." (PMID 36647073, 2023). "Two cases presenting the co-occurrence of F3T3 and an FGFR3 K650T activating mutation have been reported; the real incidence among F3T3 gliomas of concurrent activating FGFR3 mutations and their prognostic value remains to be defined." (PMID 38067258, 2023). "FGFR inhibitors showed promising efficacy in recurrent gliomas harboring FGFR1 or FGFR3 point mutations or FGFR3-TACC3 fusions." (PMID 36998447, 2023). "Taking all subtypes of glioma as a whole, we observed that FGFR3 expression demonstrated very limited association with other RTKs in all three datasets." (PMID 27829236, 2016). "Alternative splicing variants of FGFR1 and FGFR3 may also enhance ligand affinity and signal output, further driving glioma cell proliferation and invasion." (PMID 41567627, 2025). "The molecular characterization of fusion-positive glioma revealed that FGFR3::TACC3 is mutually exclusive with IDH and H3 mutation but it is often associated with TERT promoter mutation and + 7/−10 chromosome copy-number changes and amplification of CDK4 and /or MDM2." (PMID 36647073, 2023). "In some gliomas, oncogenic FGFR3-TACC3 (Transforming Acidic Coiled-Coil containing proteins) or FGFR1-TACC1 fusions cause constitutive FGFR3 or FGFR1 activation, promoting tumour growth." (PMID 40467542, 2025). "Taken together, these findings suggest a wide spectrum of radiological appearances in FGFR3::TACC3 fusion-positive gliomas." (PMID 40417325, 2025). "In this review, we summarize the histopathological and molecular features of F3T3 gliomas, the current challenges in the diagnosis and classification of these tumors, and methods for detecting FGFR3::TACC3 fusion in tumor tissue." (PMID 38730596, 2024). "In a study, next-generation sequencing demonstrated higher sensitivity in identifying FGFR3::TACC3 fusions in gliomas than RT-PCR performed on frozen tissue." (PMID 38730596, 2024). "The similarity in morphology and the inclusion of FGFR3 fusions as a diagnostic criterion have likely led to confusion and overlap between PLNTY and F3T3 gliomas." (PMID 38730596, 2024). "Diffuse gliomas with FGFR3::TACC3 fusion display unique histopathological and molecular features, including an oligodendroglioma-like appearance, calcifications, and CD34 extravascular immunoreactivity." (PMID 38730596, 2024). "Assessment of FGFR3 immunohistochemical expression represents a useful screening tool for the identification of F3T3 gliomas with FGFR3::TACC3 fusion." (PMID 38730596, 2024). "Specifically, our case harbored endocrinoïd and “oligodendrocyte-like” morphology, as well as calcifications, which are morphological hallmarks of FGFR3-fused gliomas." (PMID 39409964, 2024). "The frequency of FGFR3::TACC3 fusion in gliomas with pathological features of low grade is more difficult to appreciate but does not exceed 4% in some studies." (PMID 36647073, 2023). "Of the 217 patients treated, 30 were affected by high-grade gliomas presenting mostly FGFR3 gene fusions." (PMID 38067258, 2023). "A cost-effective, time-saving approach for the prospective screening of F3T3 fusions in glioma patients includes a first step with FGFR3 IHC." (PMID 38067258, 2023).
glioma (continued). "In contrast, gliomas with FGFR3(Ex17)::TACC3(Ex10) fusion had a significantly better OS (p = 0.032) but PFS was not significantly different (p = 0.328)." (PMID 36647073, 2023). "Patients with glioma harbored FGFR3 fusions were reported to have responded well to FGFR inhibition, and these FGFR3 fusions have been proposed as novel therapeutic targets in glioma." (PMID 34160364, 2021). "CCAT1 promotes glioma tumourigenesis by sponging miR-181b through its regulation of FGFR3 and PDGFRα." (PMID 29552296, 2018). "Clinical investigation showed that higher FGFR3 expression predicted improved survival for glioma patients, especially in Proneural subtype." (PMID 27829236, 2016). "FGFR3 showed very limited correlation with other common receptor tyrosine kinases, and predicted improved survival for glioma patients." (PMID 27829236, 2016). "As a receptor tyrosine kinase, FGFR3 showed very limited correlation with other common receptor tyrosine kinases, and predicted improved survival for glioma patients, especially for Proneural subtypes." (PMID 27829236, 2016). "To find out the role of FGFR3 in glioma, we obtained nearly 1000 glioma samples from CGGA and TCGA network." (PMID 27829236, 2016). "Taking advantage of CGGA and TCGA projects, we gathered expression data of nearly 1000 glioma samples to take an integrative investigation of FGFR3." (PMID 27829236, 2016). "When taking all gliomas into account, patients who had higher FGFR3 expression in their tumors showed much improved survival than those had lower FGFR3 expression, both in CGGA and TCGA dataset (Log-rank test)." (PMID 27829236, 2016). "FGFR3 was an independent prognostic factor, which further strengthen the protective role of FGFR3 in glioma." (PMID 27829236, 2016). "This consolidated the presumption FGFR3 correlated with relatively differentiated cellular function and less malignancy in glioma." (PMID 27829236, 2016). "FGFR3 expression data of glioma was obtained from Chinese Glioma Genome Atlas (CGGA) and TCGA (The Cancer Genome Atlas)." (PMID 27829236, 2016). "We also detected a single FGFR3–TACC3 fusion in a novel indication, papillary renal carcinoma, and a novel FGFR3–ELAVL3 fusion in low-grade glioma." (PMID 25204415, 2014). "Although no FGFR3 gene fusions were found in pediatric gliomas, FGFR1 K656E mutation is more frequent and appears to be the dominant form of mutation." (PMID 40510032, 2025). "These imaging findings may also reflect microcalcifications frequently reported in the histopathology of FGFR3::TACC3 fusion-positive gliomas." (PMID 40417325, 2025). "For clinical translation, FGFR3 immunohistochemistry (IHC) has been established as a useful screening tool for detecting FGFR3 alterations and can be incorporated into the diagnostic workflow for IDH-wildtype gliomas." (PMID 41567627, 2025). "Previous radiological imaging studies of FGFR3::TACC3 fusion-positive gliomas have reported a tendency for these tumors to localize to the cortex or subcortical white matter, particularly in the frontal or temporal lobes, with relatively well-circumscribed margins in a subset of cases based on MRI." (PMID 40417325, 2025). "Furthermore, while less frequent, FGFR1 and FGFR3 amplifications occur in adult high-grade gliomas, contributing to receptor overexpression and ligand-independent signaling." (PMID 41567627, 2025). "Diffuse gliomas with fibroblast growth factor receptor 3 (FGFR3) and transforming acidic coiled-coil containing protein 3 (TACC3) gene fusion represent a distinct molecular subtype of isocitrate dehydrogenase (IDH)-wildtype gliomas characterized by unique histopathological features." (PMID 40417325, 2025). "Diffuse gliomas with FGFR3::TACC3 fusion (F3T3 gliomas) may potentially be treated with FGFR inhibitors." (PMID 38730596, 2024).
glioma (continued). "However, trials testing the efficacy of FGFR inhibitors in patients with F3T3 gliomas have demonstrated only moderate efficacy in comparison to the remarkable results obtained in other cancers harboring the FGFR3::TACC3 fusion." (PMID 38730596, 2024). "In addition to the epigenetic heterogeneity, we also observed that the clinical behavior of glioma with FGFR3::TACC3 fusion was also heterogeneous with some patients that had a stable disease in contrast to others." (PMID 36647073, 2023). "Importantly, fewer than 15 FGFR3::TACC3 pediatric gliomas, presenting initially with LGG histological features, have been reported to date, including one case of PLNTY with secondary malignant transformation." (PMID 36647073, 2023). "Interestingly, the FGFR3::TACC3 fusion is considered an FGFRi predictive biomarker in gliomas (NCT02824133, NCT04424966) and cholangiocarcinoma (NCT03773302)." (PMID 36142417, 2022). "Remarkably, FGFR3-TACC3 positive gliomas were reported to possess specific morphological features that might reflect an initial step of tumorigenesis, as they can not only be found in glioblastoma, but also in FGFR3-fusion-positive lower grade glioma." (PMID 35955806, 2022). "Previous studies reported that FGFR3 genetic fusion was most common in glioma, followed by BLCA." (PMID 34160364, 2021). "FGFR3 fusion with TACC3 was the classic fusion type that happened in glioma." (PMID 34160364, 2021). "Moreover, recently, gene fusions involving FGFR3 have been observed in some cancer types, and glioma harbors the highest FGFR3 fusion rate." (PMID 34160364, 2021). "Although FGFR-fusion positive GBM constitutes a small subset of GBM as a whole (~ 3%), the sheer preponderance of GBM relative to other types of glioma renders this the most common scenario in which FGFR3 fusions will be encountered in most neuropathology practice settings." (PMID 32085805, 2020). "Intracranial FGFR3 gene fusions have been only detected in IDH wild-type diffuse gliomas, suggesting that FGFR3 fusions may contribute to the characteristics of this highly aggressive and invasive type of glioma." (PMID 28468611, 2017). "Moreover, FGFR3 showed very limited relevance with other receptor tyrosine kinases in glioma at transcriptome level." (PMID 27829236, 2016). "We set out to investigate the role of FGFR3 in glioma through transcriptomic analysis." (PMID 27829236, 2016). "Strong immunoexpression of FGFR3 was reported in the majority of F3T3 gliomas and mainly in areas showing the typical recurrent morphological features, suggesting that neoplastic cells in these zones could have the highest activation of FGFR3 downstream signaling." (PMID 38730596, 2024). "Furthermore, the role of FGFR3 in glioma remains undetermined." (PMID 27829236, 2016). "Moreover, FGFR3 tended to express more in lower grade gliomas (Student's t-test)." (PMID 27829236, 2016). "In gliomas, FGFR overexpression or gene fusion events, notably the FGFR3-tyransforming acidic crimp 3 (TACC3) fusion, can aberrantly activate these downstream pathways, promoting tumor cells proliferation, migration, and invasion." (PMID 41567627, 2025). "In glioma, FGFR abnormalities occur in approximately 8% of tumours, mainly affecting FGFR1 and FGFR3." (PMID 40467542, 2025). "Chromosomal translocations that fuse the tyrosine kinase domains of FGFR1 or FGFR3 and TACC1 or TACC3 have been identified in 2% to 4% of gliomas." (PMID 39087020, 2024). "The RNA sequencing analysis of 140 samples of the two cohorts ‘gliomas and BM revealed samples with gene rearrangements that involve NTRK3, FGFR3, ERG, EGFR, or MET genes in seven samples (5%)." (PMID 39087020, 2024). "As already mentioned, IHC targeting the N-terminus of FGFR3 is a useful tool for the identification and characterization of F3T3 gliomas." (PMID 38067258, 2023).
glioma (continued). "In our series of diffuse gliomas with FGFR3::TACC3 fusion, PFS (p = 0.029) and OS (p = 0.001) were significantly worse in gliomas demonstrating FGFR3(Ex17)::TACC3(Ex11) fusion." (PMID 36647073, 2023). "We found that the most common FGFR alterations in gliomas were FGFR1 SVs, as seen in other studies (along with FGFR3 alterations)." (PMID 36462464, 2022). "Four genes showed a higher fusion rate in OAs included NAB2 (0.4% vs. 4.2%) and STAT6 (0.4% vs. 2.9%) in soft tissue sarcoma and FGFR3 (0.4% vs. 3.1%) and TACC3 (0 vs. 3.0%) in glioma." (PMID 36433963, 2022). "CCAT-1 sponges miR-181b and regulates the de-repression of endogenous targets fibroblast growth factor receptor 3 (FGFR3) and PDGFR-α, thus promoting glioma tumourigenesis." (PMID 33800703, 2021). "The FGFR3 fusion types observed in glioma (GBM and LGG) in our analysis included FGFR3-TACC3, TACC3-FGFR3, FGFR3-AMBRA1, FGFR3-ELAVL3, FGFR3-FBXO28, and TACC3 was observed to be the most common partner gene of FGFR3 fusion." (PMID 34160364, 2021). "Recently, several genes have been reported to be prognostic factors in gliomas, such as IDH1, FGFR3, Notch1." (PMID 30524204, 2018). "Among glioma subtypes, activating FGFR1 alterations have been observed in a subpopulation of pilocytic astrocytomas while FGFR3 fusions occur in IDH wild-type diffuse gliomas, resulting in high FGFR3 protein expression." (PMID 28468611, 2017). "Concomitantly, the mean EGFR, ERBB2, FGFR3, and PDGFRB mRNA levels were statistically lower than those of IDH-wildtype gliomas, which also exhibited a marked increase in EGFR and ERBB2 protein abundance." (PMID 27852048, 2017). "We observed increased DNA methylation in EGFR, ERBB2, ERBB3, FGFR3, and PDGFRB in IDH-mutant gliomas as the mean methylation of each gene was statistically greater than that of IDH-wildtype." (PMID 27852048, 2017). "Amplifications and mutations of PDGFRA, KIT and KDR were found in 8-15% of RMPAhigh gliomas, followed by EPHB3 (7.7%), FGFR1 (5.9%), FGFR3 (5.9%) and MET (4.1%)." (PMID 27385209, 2016). "FGFR3::TACC3 fusion has been identified in approximately 4% of diffuse gliomas, IDH-wildtype, highlighting the distinct molecular and pathological characteristics that distinguish it from other glioma subtypes [2,]." (PMID 40417325, 2025). "The 8 low-grade gliomas harbored alterations in BRAF, KRAS, FGFR3, and MN1." (PMID 40980447, 2025). "As illustrated by our case, which ultimately matched with the diagnosis of DNET (with a cs of 0.7), there is no specific epigenetic MC for FGFR3-fused gliomas." (PMID 39409964, 2024). "Notably, high-grade F3T3 gliomas had a significantly lower mitotic rate and a higher vascular density than GBM IDH-wildtype devoid of the FGFR3::TACC3 fusion." (PMID 38730596, 2024). "It should be noted that F3T3 gliomas lacking pTERT mutations, those having other FGFR3::TACC3 fusions besides FGFR3 (ex17)::TACC3 (ex11), or those resected from patients younger than 40 years exhibit a significantly better prognosis." (PMID 38730596, 2024). "Diffuse gliomas with FGFR3::TACC3 fusion are not recognized as a distinct tumor type in the 2021 WHO classification of CNS tumors, which is in keeping with their clinical and epigenetic heterogeneity." (PMID 36647073, 2023). "These specific morphological features are reported to be present, at least focally, in 73% of FGFR3-fusion-positive tumors; however, as gliomas are known to be very heterogeneous, not all tumor areas reflect these features." (PMID 35955806, 2022). "In glioma, FGFR3 is regulated negatively by miR-99a, while in cervical cancer, FGFR3-TACC3, which has lost the FGFR3 3′ UTR region, has been proven to be a carcinogenic fusion that activates the MAPK pathway by increasing its FGFR3 signal." (PMID 34381020, 2021).
glioma (continued). "While induction of the Bcan-Ntrk1 rearrangement readily resulted in high-grade gliomas, we never observed tumours after implantation of Fgfr3-Tacc3, Sec61g-Egfr or Gga2-Prkcb positive cell populations within the timeframe of analysis (150 days)." (PMID 28695888, 2017). "Our study also revealed new cancer types harbouring known fusions (for example, BRAF fusion in rectal adenocarcinoma, FGFR3 fusion in prostate adenocarcinoma, RET fusions in colon adenocarcinoma and invasive breast carcinoma, EGFR–SEPT14 in low-grade glioma, and so on)." (PMID 25204415, 2014). "Three significant pathways were identified–FGFR3 signaling in chondrocyte proliferation and terminal differentiation, nanoparticle-mediated activation of receptor signaling, and MYCN to transcriptional activation–each of which shows mechanistic or therapeutic relevance to IDH-wildtype gliomas." (PMID 41356219, 2025). "However, the radiological imaging characteristics of FGFR3::TACC3 fusion-positive gliomas have not yet been fully elucidated, posing challenges in distinguishing them from other diffuse gliomas." (PMID 40417325, 2025). "Therefore, we conclude that increased ERBB3 abundance and PIK3R1 expression and decreased ERBB2, FGFR3, and AKT2 expression may explain the improved LGG patient survival in IDH-mutant gliomas compared with IDH-wildtype gliomas." (PMID 27852048, 2017). "Furthermore, one case reported as PLNTY and harboring FGFR3::TACC3 fusion displayed a clinical course atypical for PLNTY and underwent malignant transformation, reinforcing the notion that PLNTY and histologically low-grade F3T3 gliomas are distinct tumor types." (PMID 38730596, 2024). "Two of the investigated tumors turned out to be negative for an FGFR3 fusion (the number of investigated cases is not published), concluding that the described recurrent morphological features are often shared by FGFR3-fusion-positive glioma, but the specificity for the molecular subtype is limited." (PMID 35955806, 2022). "Beyond these canonical TACC partners, next-generation sequencing has revealed a spectrum of noncanonical fusions (e.g., FGFR3-FASN, FGFR3-BAIAP2L1) in both primary and recurrent gliomas." (PMID 41567627, 2025). "In the present study, we sought to investigate the clinical significance of FGFR3 and FGFR1 expression in two different nondiffuse gliomas: ependymomas and pilocytic astrocytomas." (PMID 28468611, 2017).